PIKFYVE (phosphoinositide kinase, FYVE-type zinc finger containing)
Diseases named in the same sentence as PIKFYVE in open-access papers (continued):
Sharing a sentence is not in itself a finding about the gene and the disease.
cancer (continued). "Since, our gene expression profiling demonstrated a number of deregulated genes (e.g., PIKFYVE, ZKSCAN1, CYR61, ITGA3) associated with the microtubule cytoskeleton, we assumed that secalonic acid’s effect on microtubules may be related to its ability to inhibit cancer cell migration." (PMID 32679716, 2020). "The viability of human cancer cells has been reported to be significantly more sensitive to PIKFYVE inhibitors relative to non-malignant (‘normal’) cell lines derived from the same tissues." (PMID 38994949, 2024). "Remarkably, PIKFYVE inhibitors can selectively terminate autophagy-dependent cancer cells and pluripotent cancer stem cells that are PIKFYVE-dependent without having any such effect on normal cells." (PMID 38994949, 2024). "WX8 (Group A) will inhibit PIP2 biosynthesis only in PIKFYVE-sensitive cancer cells; Group A PIKFYVE inhibitors do not affect the viability of normal cells under conditions where they induce PIKYVE-dependent cell death." (PMID 38994949, 2024). "Of the four groups of PIKFYVE inhibitors, only those in Group A would selectively terminate PIKFYVE-dependent (autophagy-dependent) cancer cells without suppressing the viability of normal cells." (PMID 38994949, 2024). "To address whether PIKfyve inhibition augments ACT, we established tumors derived from OVA-expressing cancer cells and infused OT1 CD8+ T cells to the tumor-bearing syngeneic hosts." (PMID 38011559, 2023). "Autophagy-dependent cancer cells are much more sensitive than non-malignant cells to WX8 and related PIKFYVE inhibitors when quantified by a loss of cellular ATP (~2000X), cell proliferation (~50X), cell permeability (~65X) or genomic DNA (~75X)." (PMID 36803256, 2023). "Collectively, our findings show that targeting PIKfyve enhances immunotherapies by elevating surface expression of MHC-I in cancer cells, and PIKfyve inhibitors have potential as agents to increase immunotherapy response in cancer patients." (PMID 38011559, 2023). "This discovery suggests that PIKFYVE-dependent cancers could be identified clinically by low levels of PIP5K1C and treated with PIKFYVE inhibitors." (PMID 36803256, 2023). "This, however, will not be the first use of a PIKfyve inhibitor in clinical trials for the treatment of various diseases, including cancer." (PMID 34977038, 2021). "Inhibitors specifically targeting the 1‐phosphatidylinositol 3‐phosphate 5‐kinase (PIKFYVE) disrupt lysosome homeostasis, thereby selectively terminating autophagy‐dependent human cancer cells in vivo as well as in vitro without harming the viability of nonmalignant cells." (PMID 38414326, 2024). "Thus, one advantage of group A inhibitors is that they would be expected to inhibit PIP3 biosynthesis in PIKFYVE-dependent cancer cells but not in normal cells." (PMID 38994949, 2024). "Thus, PIKFYVE inhibitors can selectively terminate autophagy‐dependent cancer cells and pluripotent cancer stem cells under conditions where nonmalignant cells remain viable." (PMID 38414326, 2024). "Whereas all cancer cells might become autophagy-dependent, all cancer cells are not PIKFYVE-dependent; some cancer cell lines are as resistant to PIKFYVE inhibitors as nonmalignant cells." (PMID 38994949, 2024). "Therefore, PIKFYVE inhibitors, either alone or in combination with other targeted drugs or genetic manipulation (including ectopic IL24 protein), exhibit significant in vitro regression of growth of PIKFYVE-sensitive cancers." (PMID 38994949, 2024). "However, these inhibitors selectively terminate PIKFYVE-dependent cancer cells and cancer stem cells with not having adverse effect on normal cells." (PMID 38994949, 2024). "This discovery suggests that clinical applications of PIKFYVE inhibitors could be identified in cancer cells by a low abundance of PIP5K1C relative to non-malignant cells." (PMID 36803256, 2023).
cancer (continued). "To determine whether PIKFYVE expression specifically in malignant cells predicts clinical outcomes of ICB-treated patients, we exploited published single-cell RNA-sequencing datasets representing cancer patients treated with ICB (45, –47)." (PMID 38011559, 2023).
infection (23 papers, 2008 to 2026). The state of being infected such as from the introduction of a foreign agent such as serum, vaccine, antigenic substance or organism. "Here, we studied the role of PIKfyve in Mycobacterium marinum (Mm) infection of zebrafish larvae using two chemical inhibitors of the enzymatic activity of PIKfyve, YM201636 and Apilimod." (PMID 42064211, 2026). "It has been reported that inhibition of PIKfyve (by apilimod) prevents viral cytoplasmic entry and infection by SARS-CoV-220." (PMID 39085352, 2024). "Two members of the WX8 family of PIKfyve inhibitors, WX8 and NDF, were tested for efficacy when treatment was initiated prior to infection with SARS-CoV-2 (B.1.351, “beta” variant, 1 × 105 plaque forming units [PFU]/mL) in Balb/c laboratory mice." (PMID 35962188, 2022). "PIKfyve inhibitor treatment was initiated in triplicate at 2 h pre-infection, at the time of infection, or 2- or 6-h post-infection with SARS-CoV-2 (WA-1), and supernatants were collected after 24 h to assess virus output by plaque assay." (PMID 35962188, 2022). "Here we analyzed the effects of apilimod, a PIKfyve inhibitor that was reported to be well tolerated in humans in phase 2 clinical trials, for its effects on entry and infection of EBOV and Marburg virus (MARV)." (PMID 28403145, 2017). "Inhibition of PtdIns-converting enzyme PIKfyve with the drug YM201636 (1 μM) from 1 h before infection to 4 hpi resulted in a significant decrease in viral replication." (PMID 28587154, 2017). "Inhibition of PtdIns-converting enzyme PIKfyve with the drug YM (1 μM) from 2 h before infection to 4 hpi as described in Materials and Methods resulted in a significant decrease in viral replication." (PMID 28587154, 2017). "This supports our proposal that apilimod blocks EBOV entry and infection through a PIKfyve-dependent pathway." (PMID 28403145, 2017). "Follow‐up perturbation analysis showed that infection required Rab7a and PIKfyve, confirming that VACV is a late‐penetrating virus dependent on macropinosome maturation." (PMID 25869659, 2015). "To elucidate whether PIKfyve inhibition contributes to cathepsin B dynamics during infection, we utilised the PIKfyve inhibitor vacuolin-1." (PMID 40274809, 2025). "Our findings suggest that pharmacological inhibition of PIKfyve and the novel PIP5K1C could represent an effective therapeutic strategy for preventing infection by SARS-CoV-2 or its variants and for preparing for future pandemics." (PMID 39085352, 2024). "We found these PIKfyve inhibitors restricted hCoV-OC43 replication in human umbilical vein endothelial cells (HUVECs) as measured by infection-induced cell death, suggesting that PIKfyve inhibitors could be a potential pan-coronavirus therapeutic." (PMID 35962188, 2022). "For example, inhibition of PIKfyve, TPCs, NHEs, or the v-ATPase could help prevent cellular infection by Ebola virus, SARS-CoV-2, and other viruses." (PMID 34249909, 2021). "We next tested the role of PIKfyve on the outcome of infection." (PMID 30730983, 2019). "We studied whether the inhibition of PIKfyve activity before infection interferes with virus production." (PMID 23133661, 2012). "Therefore, we also used apilimod, an FDA-approved PIKfyve inhibitor, to block macropinocytosis, and determine whether this has an effect on infection." (PMID 39028694, 2024). "Moreover, we demonstrate that cells lacking PIKfyve are more susceptible to infection by the intracellular pathogen Legionella pneumophila." (PMID 30730983, 2019). "Since apilimod targets PIKfyve, since PIKfyve is required for EBOV entry and infection, and since apilimod blocks EBOV entry and infection, we reasoned that apilimod blocks EBOV entry and infection by targeting PIKfyve." (PMID 28403145, 2017). "Conversely, inhibition of Akt, which is normally activated by the PI3 kinase and itself activates PIKfyve during EGFR endocytosis, leads to an increase in levels of Rab7 on chlamydial endosomes while reducing internalization and infection." (PMID 28787457, 2017).
infection (continued). "Interestingly, when analogous experiments were performed with the inhibitor of PIKfyve activity, which blocks endosome maturation, resulting in enlarged EEs that cannot progress to late endosomes, we saw a massive increase in EB internalization (230%) and subsequent infection." (PMID 28787457, 2017). "Maturation of macropinosomes involving Rab5 was evidently a critical step in infection, whereas later stages in maturation coordinated by Rab7 and PIKfyve were not essential." (PMID 23593008, 2013).
tumor (16 papers, 2018 to 2026). "It was also demonstrated that the knockdown of PIKfyve in Myc-CaP prostate cancer cells had tumor-inhibitory effects in both immune-competent and deficient mice, but the antitumor properties were maximized in a competent immune environment." (PMID 35892678, 2022). "Co-inhibition of mTOR and PIKfyve synergistically disrupts lipid and iron metabolism, leading to enhanced tumor suppression and improved survival in preclinical GEP-NET models." (PMID 41881024, 2026). "To determine the impact of PIKfyve inhibition on PDAC tumour growth, we used in vivo allograft and xenograft models to test the efficacy of ESK981." (PMID 40269157, 2025). "To this end, we sought to evaluate PIKfyve as a therapeutic target in PDAC and found that genetic knockout or pharmacological inhibition of PIKfyve markedly reduced PDAC tumour development and growth." (PMID 40269157, 2025). "We next evaluated the role of Pikfyve in the KPC model to assess the effect of PIKfyve on tumour progression." (PMID 40269157, 2025). "Autophagy inhibition using small molecule inhibitors of ULK1 or PIKfyve was shown to increase responses to ICB in tumor‐bearing mice." (PMID 38506049, 2024). "We then assessed the effects of PIKfyve inhibitor treatment on tumor infiltrating DCs and T cells isolated from DC-selective Pikfyve KO versus WT mice in multiple tumor models." (PMID 38942798, 2024). "Previous work illustrated that inhibition of PIKfyve disrupted autophagy flux and lysosome function, leading to increased immune activity and tumor suppression in multiple cancer models." (PMID 38562800, 2024). "The combination of an immune checkpoint inhibitor and a PIKfyve inhibitor markedly increases complete tumor regression." (PMID 38994949, 2024). "Together, these results suggest a role for targeting PIKfyve to alter DC phenotypes and DC-dependent therapies in the tumor microenvironment." (PMID 38942798, 2024). "Our preclinical studies demonstrate that PIKfyve inhibitors target DCs directly, require DCs and DC/T cell signaling to prevent tumor progression, and potentiate ICB therapy." (PMID 38464258, 2024). "First, we treated non-tumor-bearing, wild-type mice with apilimod, a potent and specific PIKfyve inhibitor that has been studied in many cell types and evaluated in Phase II clinical trials." (PMID 38942798, 2024). "Although the therapeutic vaccine alone showed only a marginal effect on tumor control, inhibition of PIKfyve strongly improved efficacy of the vaccine, resulting in significant extension of survival." (PMID 38011559, 2023). "PIKfyve, a recently explored lipid kinase, has been shown to correlate with tumor activity and immune checkpoint blockades." (PMID 35892678, 2022). "Combination treatments of PIKfyve knockdown with anti-PD-1 therapy led to significant increases in complete tumor regression, further supporting the inhibitory role PIKfyve plays in immunosuppressive signaling." (PMID 35892678, 2022). "In this study, we investigate the effect of APY0201, an inhibitor of PIKfyve, on GC tumor growth and its mechanism of action." (PMID 36245991, 2022). "Tumor cells incubated with 200 nM PIKfyve inhibitor YM201636 for 24 h displayed a higher ability of migration." (PMID 30445978, 2018). "Finally, we assessed the effects of PIKfyve inhibitor treatment on tumor-infiltrating DCs isolated from DC-selective Pikfyve KO versus WT mice." (PMID 38464258, 2024). "Combined, these data show that PIKfyve in DCs can modulate tumor outcomes in vivo." (PMID 38464258, 2024). "In a proof-of-concept experiment, we explored whether PIKfyve inhibition, as a DC-maturing and DC-dependent therapy, could potentiate the effects of PolyI:C against tumor growth in vivo." (PMID 38464258, 2024).
tumor (continued). "Either ablation of the PIKFYVE gene in dendritic cells or apilimod inhibition of PIKFYVE restrained tumor growth, enhanced dendritic cell-dependent T-lymphocyte immunity, and potentiated the efficacy of the immune checkpoint blockade in tumor-bearing mouse models." (PMID 38994949, 2024). "Finally, we show that treatment with a PIKfyve inhibitor potentiates vaccine-mediated tumor growth reduction in vivo." (PMID 38942798, 2024). "Importantly, PIKfyve inhibition by apilimod or ESK981 also led to upregulation of tumor-specific MHC-I surface expression and an increase in intratumoral activated CD8+ T cells." (PMID 38011559, 2023). "Finally, we leverage targeted lipid fluxomics and the distinct ganglioside and globoside profiles of tumor and stromal cells, respectively, to demonstrate the role of the lipid kinase PIKfyve in supporting ganglioside homeostasis via sialic acid and ceramide salvage." (PMID 42039671, 2026). "Importantly, consistent with our tumor studies, PIKfyve perturbation through PIKFYVE knockdown substantially slowed the growth of PDAC cells, and PIKfyve inhibition decreased PDAC cell viability with half-maximal inhibitory concentrations (IC50) in the nanomolar ranges for most cell lines." (PMID 38562800, 2024). "However, whether and how PIKfyve serves as a target for upregulating tumor-specific MHC-I surface expression and whether apilimod or ESK981 treatment augments CD8+ T cell–dependent immunotherapies remain to be explored." (PMID 38011559, 2023). "In addition, the mutation frequencies of UNC13C, PIKfyve, and CAPN9 were significantly different between EUR and AFR (p < 0.05) and might affect prognosis by regulating tumor proliferation and apoptosis." (PMID 34950653, 2021). "Accordingly, simultaneously targeting PIKfyve and KRAS–MAPK resulted in the elimination of the tumour burden in numerous preclinical human and mouse models." (PMID 40269157, 2025). "Taken together, these data show that PIKfyve inhibition decreases proliferation, induces apoptosis, and dramatically suppresses growth in both murine and human PDAC tumor models." (PMID 38562800, 2024). "Accordingly, the simultaneous targeting of PIKfyve and KRAS-MAPK resulted in the elimination of tumor burden in a syngeneic orthotopic model and tumor regression in a xenograft model of PDAC." (PMID 38562800, 2024). "In addition, we discovered that PIKfyve may preferentially alter cDC1s in tumor models." (PMID 38464258, 2024). "Together, our findings suggest that PIKfyve inhibition impairs autophagy, upregulates surface MHC-I, and, thus, controls tumor growth in a CD8+ T cell- and MHC-I-dependent manner." (PMID 38011559, 2023). "In the syngeneic models, we found that oral gavage of the phase I-cleared PIKfyve inhibitors, apilimod or ESK981, significantly augmented ICB in both primary tumor and metastasis settings." (PMID 38011559, 2023). "Pharmacological inhibition of PIKfyve with apilimod or ESK981 also showed similar effects in 7940B and Panc 04.03 (human PDAC) cells, as well as in vivo in UM-2 pCDX tumours." (PMID 40269157, 2025). "To assess whether PIKfyve inhibition enhances efficacy of ACT, we established s.c. tumors derived from OVA-expressing B16-F10 cells and infused CD8+ T cells derived from OT1 mice into the tumor-bearing syngeneic hosts." (PMID 38011559, 2023). "To assess the impact of PIKfyve inhibition on non-KRAS-driven PDAC, we employed a BxPC-3 (BRAFV487-P492>A) CDX and showed that ESK981 still suppressed tumor growth and reduced tumor weight at endpoint." (PMID 38562800, 2024).
neurodegenerative disease (6 papers, 2011 to 2025). A disorder of the central nervous system characterized by gradual and progressive loss of neural tissue and neurologic function. "We found that PIKfyve is acylated by the two acyltransferases, zDHHC9/21, which are highly expressed in the brain and are associated with neurodegenerative diseases." (PMID 34291577, 2021). "These beneficial cellular responses position PIKfyve as a potential therapeutic target for disorders characterized by lysosomal dysfunction, particularly neurodegenerative diseases where failure of lysosomes to clear protein aggregates is a key feature." (PMID 41315403, 2025). "It is extremely well documented that dysfunction of the PIKfyve complex can lead to serious neurodegenerative diseases, including CMT4J, ALS and the more recently described Yunis–Varón syndrome." (PMID 26934981, 2016). "This mechanistic framework may explain the paradoxical therapeutic effects of acute PIKfyve inhibition in neurodegenerative disease models, despite the pathological consequences of genetic PIKfyve/Fig4/Vac14 dysfunction." (PMID 41315403, 2025). "Together, this draws attention to investigating the potential mechanistic link between PIKfyve activity and TRPML1 function in the context of EAL neuropathogenesis in LOAD and other neurodegenerative diseases." (PMID 36825945, 2023). "Collectively, these studies draw attention to the potential role of the PIKfyve complex in EAL defects in AD and other related neurodegenerative diseases." (PMID 36825945, 2023).
neurological diseases (5 papers, 2018 to 2025). "Our data demonstrates that disruption of INPP4B/PIKfyve‐dependent lysosome reformation leads to protein aggregate accumulation and proteotoxicity, processes that are associated with neurological disease." (PMID 35968799, 2022). "PIKFYVE is involved in several neurological diseases and it plays an important role in maintenance of lysosomal functioning, endosomal trafficking, and autophagy, and it was recently shown to be a relevant target to alleviate ALS pathology." (PMID 39009412, 2024). "It is interesting to speculate whether reduced lysosome reformation and increased proteotoxic stress may contribute to neurological disease resulting from PIKfyve complex inactivation, and in turn, whether dysregulation of lysosome reformation from endolysosomes may impact on other human diseases." (PMID 35968799, 2022). "Similarly, the PIKfyve gene-trap mouse also had severe neurologic disease, which ultimately resulted in early lethality, making it difficult to assess whether PIKfyve regulates melanogenesis." (PMID 29584722, 2018).
genetic diseases (2 papers, 2016 to 2024). "Taken together these genetic diseases highlight the significance of the PIKfyve pathway for neuronal function and integrity." (PMID 26934981, 2016).
immune dysfunction (2 papers, 2023 to 2024). "Considering the hypothesis regarding the causes of the immune dysfunction in C9ORF72 knockout mice, it seems likely that apilimod or other PIKfyve inhibitors could rescue this phenotype as well." (PMID 37138765, 2023).
hematological malignancies (1 paper, 2020). "Data specifically focused on PIKfyve inhibition in hematological malignancies has been subsequently published." (PMID 32393731, 2020).